GPX4 (glutathione peroxidase 4)
Diseases named in the same sentence as GPX4 in open-access papers (continued):
Sharing a sentence is not in itself a finding about the gene and the disease.
kidney (3 papers, 2022 to 2025). "Various studies have shown that decreased Gpx4 levels in kidney diseases increase lipid peroxidation and lead to kidney dysfunction." (PMID 40538499, 2025). "The excessive production of lipid ROS and suppression of GPX4 reduced host defenses against oxidative stress and thus mediated the onset of ferroptosis in prostatitis." (PMID 35755168, 2022). "Here, we confirmed that the downregulation of SOD, GSH, and GPX4 levels; the upregulation of Slc7a11, Acsl4, Cox2, 4-HNE, MDA, and Fe2+ levels; and kidney dysfunction all occur in the AKI mouse model." (PMID 35979396, 2022). "In this study, the inactivation of the system Xc−/GPX4 axis, accumulation of iron, and activation of ACSL4/LPCAT3 axis strongly highlighted the important role of ferroptosis on prostatitis development." (PMID 35755168, 2022). "Moreover, elevated iron concentration and differential expression of ferroptosis indicators, including GPX4, SLC7A11/Xc−, ACSL4, LPCAT3, and PTGS2, implied that ferroptosis engaged in the development of prostatitis in the context of iron overload and oxidative damage." (PMID 35755168, 2022).
lupus nephritis (3 papers, 2016 to 2025). Glomerulonephritis in the context of systemic lupus erythematosus. "Downregulation of GPX4 expression and accumulation of lipid peroxides in lupus nephritis (LN) renal tissue further implicate ferroptosis in immune-mediated kidney injury." (PMID 40852352, 2025). "In contrast, in the kidney, the expression of genes involved in pyroptosis, e.g. NLRP3 and CASP1 were significantly increased and TNFR1, RIPK1, RIPK3, CIAP1/2 and GPX4 were significantly decreased along the progression of lupus nephritis (LN)." (PMID 27811014, 2016). "Similarly, GPX4 overexpression in systemic lupus erythematosus nephritis promotes glomerular injury and lupus nephritis through ferroptosis pathways." (PMID 37823298, 2024).
lymph node metastasis (3 papers, 2023 to 2025). "We also examined whether the combined FSP1 and GPX4 expression pattern was associated with NAC in patients with ≥ T2 or lymph node metastasis." (PMID 36576648, 2023). "Cox univariate survival analysis indicated that prognosis was influenced by lymph node metastasis (p = 0.002), tumor location (p = 0.02), clinical stage (p = 0.0007), and GPX4 expression." (PMID 40746894, 2025). "The prognostic comparison of the patients with ≥ T2 or lymph node metastasis among the same three groups categorized according to the FSP1 and GPX4 expression revealed a pattern that was similar to that observed in the entire patient population." (PMID 36576648, 2023). "The GPX4-positive group had significantly higher invasion depth (p = 0.014), lymph node metastasis (p = 0.001), lymphatic involvement (p = 0.019), vascular involvement (p = 0.011), and disease stage (p = 0.002) than the GPX4-negative group." (PMID 36576648, 2023).
metastatic tumors (3 papers, 2020 to 2022). "Western blot analysis showed that the expression levels of SCD1, FADS2, GPX4, and TFR1 in omental metastatic tumors were relatively higher than their counterpart primary tumor tissues." (PMID 35547771, 2022).
motor neuron disease (3 papers, 2021 to 2024). "GPX4 knockout can induce cell death in a pathologically relevant form of ferroptosis, while GPX4 overexpression can delay motor neuron disease in SOD1G93A mice by inhibiting ferroptosis." (PMID 38367173, 2024). "GPX4 knockout studies revealed motor neuron disease phenotypes as a consequence of (selective) motor neuron loss." (PMID 38666827, 2024). "Genetic depletion of GPX4, a central repressor of ferroptosis, induced motor phenotypes suggestive of motor neuron diseases accompanied by a more or less selective motor neuron degeneration." (PMID 38666827, 2024). "In conclusion, our results from this study indicate that enhanced function of Gpx4 retards motor neuron disease of SOD1G93A mice, likely through a mechanism of suppressing ferroptosis of motor neurons." (PMID 34145375, 2021). "In this study, to determine the role of ferroptosis in motor neuron degeneration in ALS, we investigated the effect of Gpx4 overexpression on motor neuron disease of SOD1G93A mice." (PMID 34145375, 2021). "To determine how Gpx4 overexpression might affect motor neuron disease triggered by SOD1G93A, we established cohorts of SOD1G93AGPX4 and control SOD1G93A mice and then proceeded to measure their lifespans." (PMID 34145375, 2021). "To determine whether increased defense against ferroptosis might affect motor neuron disease, we were interested in determining how increased function of Gpx4 might affect lifespan and motor neuron degeneration of SOD1G93A mice." (PMID 34145375, 2021). "To assess the effect of increased protection against ferroptosis on motor neuron disease, we generated SOD1G93AGPX4 double transgenic mice by cross-breeding GPX4 transgenic mice with SOD1G93A mice, a widely used ALS mouse model." (PMID 34145375, 2021).
neutropenia (3 papers, 2023 to 2025). A decrease in the number of neutrophils found in the blood. "Neutrophil-specific Gpx4 haplosufficiency mirrors key clinical features of human SLE, including autoantibodies, neutropenia, skin lesions and proteinuria, suggesting that neutrophil ferroptosis leads to neutropenia and disease manifestations in SLE134." (PMID 37612410, 2023).
non-alcoholic steatohepatitis (3 papers, 2022 to 2025). "CSP inhibits the AMPK-mTOR pathway, restores autophagy and ferroptosis markers such as GPX4 and Nrf-2, and alleviates non-alcoholic steatohepatitis by inhibiting autophagic ferroptosis." (PMID 41050396, 2025).
oligospermia (3 papers, 2022 to 2024). Decreased number of spermatozoa in the semen. "Knockout of Nrf2 leads to spermatogenic cell ferroptosis and results in oligospermia by inhibiting the SLC7A11/GSH/GPX4 metabolic pathway, increasing intracellular iron entry, and inhibiting iron exporters." (PMID 36558426, 2022). "Ferroptosis of testicular spermatogenic cells in adult mice is due to downregulation in the expression of nuclear factor E2–related factor 2 (Nrf2) and glutathione peroxidase 4 (GPX4), and reduction of iron transport protein 1 (FPN1) expression by busulfan, which leads to oligospermia." (PMID 37801247, 2023).
parasite (3 papers, 2020 to 2025). "Specifically, blocking GPX4 or SLC7a11 dramatically reduces Plasmodium liver stage parasite infection." (PMID 31065106, 2020).
rectal cancer (3 papers, 2019 to 2023). A primary or metastatic malignant neoplasm that affects the rectum. "The expression of GPX4 in rectal cancer tissues was higher than that in normal tissues, and the survival rate of the high GPX4 expression group showed a downward trend." (PMID 37658132, 2023).
squamous cell carcinoma (3 papers, 2013 to 2024). A carcinoma arising from squamous epithelial cells. "In squamous cell carcinoma of the lung cell lines, synergistic cell death resulting from GPX4 and FSP1 inhibition by RSL3 and iFSP1 is through iron-dependent ferroptosis." (PMID 39273151, 2024).
Type 1 diabetes (3 papers, 2021 to 2023). "For example, some of the most significantly altered MAM proteins in our Type 1 diabetes model included LGALS3, GPX4, PDGFR, AQP4, and alphaA- and alphaB-crystallin (CRYAA and CRYAB)." (PMID 36139394, 2022).
adrenocortical cancer (2 papers, 2020 to 2023). "We further analyzed the expression levels of ACSL4 and GPX4 in three adrenocortical cancer cell lines NCI-H295R30, CU-ACC1 and CU-ACC231 which were subsequently used for all further experiments." (PMID 32184394, 2020).
bone cancer (2 papers, 2023 to 2025). A primary or metastatic malignant neoplasm affecting the bone or articular cartilage. "It promotes ferroptosis in bone tumor cells by inducing oxidative stress, depleting GPX4, increasing ROS levels, and activating the MAPK signaling pathway." (PMID 40740786, 2025). "This analysis revealed that bone cancer and soft tissue sarcoma cell lines have high GPX4 dependency." (PMID 37444594, 2023).
brain tumor (2 papers, 2020 to 2023). "Decreased expression of GPx1 in brain tumor cells leads to increased sensitivity to oxidative stress, while inhibition of GPx4 leads to the accumulation of lipid hydroperoxides and ferroptotic cell death." (PMID 33134322, 2020).
Breast invasive carcinoma (2 papers, 2023 to 2025). "Interestingly, GPX4 expression was not significantly decreased, except in breast invasive carcinoma." (PMID 36626251, 2023).
chronic hepatitis B (2 papers, 2024). "This study aimed to investigate the clinical significance of glutathione peroxidase 4(GPX4) in the occurrence and development of chronic hepatitis B (CHB)." (PMID 38515187, 2024).
chronic myeloid leukemia (2 papers, 2024 to 2025). "Similarly, Hyperoside induces ferroptosis in chronic myeloid leukemia cells by targeting the Nrf2/SLC7A11/GPX4 axis, with molecular docking, DARTS, and CETSA experiments demonstrating its high affinity for Nrf2." (PMID 40917752, 2025).
colorectal tumors (2 papers, 2022 to 2024). "Treatment with tempol, a superoxide dismutase mimetic radical scavenger, suppressed GPX4 deficiency-induced colorectal tumors." (PMID 38260380, 2024).
dry eye (2 papers, 2016 to 2024). "Deficient GPx4 can aggravate the corneal pathology and may highlight a new therapeutic target for corneal disorders such as dry eye and keratoconjunctivitis." (PMID 28203523, 2016). "In the present study, we established a dry eye model in vitro and in vivo to elucidate whether AST inhibits ferroptosis via regulating SLC7A11/GPX4 and activates autophagy to protect against DED." (PMID 39224780, 2024). "In addition, in a dry eye mouse model, AST upregulated SLC7A11 and GPX4 and inhibited ferroptosis." (PMID 39224780, 2024).
E. coli infection (2 papers, 2024 to 2025). "E. coli infection suppresses solute carrier family 7-member 11 (SLC7A11)/glutathione peroxidase 4 (GPX4) expression in bovine mammary epithelial cells (BMECs), disrupts iron homeostasis and precipitates ferroptosis." (PMID 41413615, 2025). "In intestinal epithelial cells (IECs), E. coli infection decreases GPX4 and ferritin heavy chain 1 (FTH1) levels and increases lipid peroxidation, thereby inducing ferroptosis." (PMID 41413615, 2025). "In accordance with the in vitro findings, PTGS2 expression in BEECs increased as the duration of E. coli infection increased, whereas GPX4 expression significantly increased at 1 h post-infection, and SLC7A11, GPX4, and FTH1 expression significantly decreased at 5 h post-infection." (PMID 41413615, 2025). "E. coli infection activates GSK-3β through dephosphorylation at Ser9, active GSK-3β binds and degrades NRF2 via the proteasome pathway, and NRF2 suppression disrupts antioxidant defenses (SLC7A11/GPX4 and GCLC/GSH) and iron homeostasis (FTH1), triggering ferroptosis in BEECs." (PMID 41413615, 2025).
Epstein-Barr virus infection (2 papers, 2021 to 2024). An infection that is caused by Epstein-Barr virus. "The difference between HBV-ACLF and non-HBV ACLF patients suggested that HBV infection may have an effect on GPX4 expression, and this phenomenon of viral influence on GPX4 expression also occurs during Epstein-Barr virus infection." (PMID 39119475, 2024).
erectile dysfunction (2 papers, 2022 to 2023). Persistent or recurrent inability to achieve or to maintain an erection during sexual activity. "In conclusion, overexpression of PRDX2 in ADSCs enhanced the therapeutic effect in a rat model of neurogenic erectile dysfunction by inhibiting ferroptosis via regulation of the GPX4/ACSL4 axis." (PMID 36819780, 2023). "The data indicate that DMED model was successfully established and that GPX4-LV injection could partially prevent erectile dysfunction in DMED rats in a dose-dependent manner." (PMID 36290619, 2022). "Our results further demonstrated changes in the expression of key proteins (GPX4 and ACSL4) in the ferroptosis pathway, whereas PRDX2-ADSCs ameliorated BCNI-induced erectile dysfunction and ferroptosis of the corpus cavernosum in NED rats." (PMID 36819780, 2023).
familial hypercholesterolemia (2 papers, 2021 to 2024). An inheritable form of hyperlipidemia, in which there are excess lipids in the blood. "Moreover, an oral fat load could induce upregulation of the GPx1 and GPx4 genes at 4 h in both familial hypercholesterolemia patients and normolipidemic volunteers." (PMID 39691690, 2024).
gallbladder cancer (2 papers, 2025). "For example, HMOX1 induces ferroptosis by inhibiting GPX4 expression in liver and gallbladder cancer." (PMID 41280724, 2025).
gastritis (2 papers, 2015 to 2022). Inflammation of the stomach. "Similarly, TCF4 and GPX4 mRNA levels were higher in H. pylori-positive human gastritis samples." (PMID 35534546, 2022). "The mRNA expression of GPX4 gene is increased 2.184-fold (primary cancer vs gastritis), and mRNA expression of MPND increased 1.3369-fold (primary cancer vs gastritis)." (PMID 26330360, 2015).
gastrointestinal stromal tumor (2 papers, 2022 to 2023). "GPX4 has been reported to be specifically reduced in imatinib-derived persister gastrointestinal stromal tumor cells." (PMID 35719967, 2022).
haemorrhage (2 papers, 2021 to 2023). "Vitamin E prevents the rapid death of neurons in conditional neuronal Gpx4 knockout mice, whereas overexpression of GPX4 protects against intracerebral haemorrhage in rats." (PMID 34099897, 2021).
hemochromatosis (2 papers, 2022 to 2023). A disorder of iron metabolism characterized by a triad of HEMOSIDEROSIS; LIVER CIRRHOSIS; and DIABETES MELLITUS. "In the ferroptosis-induced RCD, hemochromatosis initiates lipid peroxidation under the circumstance with the inhibited activity of glutathione peroxidase-4 (GPX-4), which is responsible for plasma membrane disruption." (PMID 35837297, 2022).
hyperhomocysteinemia (2 papers, 2025). A serious metabolic condition caused by mutations in the MTHFR gene, medications, or nutritional deficiency. "Based on our research findings, β-catenin or GPX4 may serve as potential biomarkers and therapeutic targets for hyperhomocysteinemia-associated myocardial injury." (PMID 40768425, 2025). "The myocardial β-catenin and GPX4 in mice with hyperhomocysteinemia were markedly lower than the control group, whereas the expression of FTH1 remained unchanged." (PMID 40768425, 2025). "Currently, there is a lack of clinical data on the dysregulation of β-catenin/GPX4 in patients with hyperhomocysteinemia." (PMID 40768425, 2025).
hyperuricemia (2 papers, 2024 to 2025). An abnormally high level of uric acid. "We found that FOXO3, Nrf2, NQO1, Gpx4 and PIK3CA are not only related to regulating metabolic diseases, but also may have therapeutic effects on aging, cancer, or hyperuricemia." (PMID 38957396, 2024). "It is suggested that the regulation of FOXO3 and GPx4 may be related to the therapeutic mechanism of improving hyperuricemia, but there is no clinical evidence to prove it." (PMID 38957396, 2024).
Leigh syndrome (2 papers, 2024 to 2025). A progressive neurological disease defined by specific neuropathological features associating brainstem and basal ganglia lesions. "The therapeutic potential of vatiquinone in vivo was assessed using the tamoxifen-induced mouse model for GPX4 deficiency and the Ndufs4 knockout mouse model of Leigh syndrome." (PMID 39930437, 2025). "The therapeutic potential of vatiquinone in vivo was assessed using tamoxifen-induced mouse model for GPX4 deficiency and the Ndufs4 knockout mouse model of Leigh syndrome." (PMID 38883711, 2024). "That scenario may include FA, genetic defects in GPX4, and other factors involved glutathione redox or iron homeostasis, but no current evidence supports the idea that 15-LO is involved in the pathobiology of mitochondrial diseases as a group or Leigh syndrome in particular." (PMID 38883711, 2024).
medulloblastoma (2 papers, 2024 to 2025). A malignant, invasive embryonal neoplasm arising from the cerebellum. "β3-depleted (β3_KO) medulloblastoma cells exhibit lipid hydroperoxide accumulation after radiotherapy, indicating ferroptosis, a regulated cell death process induced by ROS and inhibited by antioxidants such as cysteine, glutathione (GSH), and glutathione peroxidase 4 (GPx4)." (PMID 39857430, 2025). "β3-depleted (β3_KO) medulloblastoma cells exhibit lipid hydroxyperoxide accumulation after radiotherapy, indicating ferroptosis, a regulated cell death induced by ROS and inhibited by antioxidants such as cysteine, glutathione (GSH), and glutathione peroxidase 4 (GPx4)." (PMID 39590175, 2024).
Miscarriage (2 papers, 2016 to 2022). A pregnancy that ends at a stage in which the fetus is incapable of surviving on its own, defined as the spontaneous loss of a fetus before the 22th week of pregnancy. "Therefore, future studies on the expression and activity of the GPX4 enzyme throughout pregnancy can pinpoint the effect of GPX4/2-methoxyestradiol at different stages of miscarriage." (PMID 35434480, 2022). "Therefore, the current study aimed to use the SNaPshot method to investigate the association between polymorphisms of pre-miR-125a (rs41275794), pre-miR-10a (rs3809783), pre-miR-323b (rs56103835), GPX4 (rs4680)and GPX4 (rs713041), and RPL in Iranian women with idiopathic recurrent miscarriage." (PMID 35434480, 2022).
ovarian clear cell cancer (2 papers, 2023). An invasive malignant neoplasm that arises from the ovary and is characterized by a predominance of clear and hobnail malignant epithelial cells. "The GPX4 is an important factor in ovarian ultrastructural changes and a potential target for treating ovarian clear cell carcinoma." (PMID 37589858, 2023). "In kidney and ovarian clear cell carcinoma, inhibition of GPX4 expression also promoted the development of ferroptosis." (PMID 37207153, 2023).
peripheral arterial disease (2 papers, 2021 to 2024). A disorder of the arteries supplying the upper and lower extremity and the visceral organs. "In addition, it has also shown that GPX4 mutations enhance the risks for aortoiliac occlusive disease and peripheral arterial disease that result in atherosclerotic occlusions." (PMID 38100883, 2024). "Among them, a GPx4 variant in the rs713041T allele enhances the risks for aortoiliac occlusive disease (AOID) and peripheral arterial disease (PAD) that result in atherosclerotic occlusions." (PMID 34376636, 2021).
pheochromocytoma (2 papers, 2019 to 2025). "Our study highlights an important role of the HIF pathway in driving ferroptosis sensitivity in cancers, and implies that a GPX4-dependent cell state may be shared by other HIF-α-active cancers, for example, pheochromocytoma and paraganglioma (PCPG)." (PMID 30962421, 2019).
pneumonia (2 papers, 2025 to 2026). An acute, acute and chronic, or chronic inflammation focally or diffusely affecting the lung parenchyma, caused by an infection in one or both of the lungs (by bacteria, viruses, fungi, or mycoplasma.). "Future studies should employ specific ferroptosis inhibitors or utilize GPX4 knockout mice to conclusively demonstrate the indispensable role of ferroptosis inhibition in mediating the anti-H1N1 and anti-pneumonia effects of RHDS." (PMID 40872344, 2025).
postmenopausal osteoporosis (2 papers, 2024 to 2025). Metabolic disorder associated with fractures of the femoral neck, vertebrae, and distal forearm. "The latest research also reports that psoraleae fructus combined with walnut kernels improves postmenopausal osteoporosis by inhibiting ferroptosis through the Nrf2/GPX4/SLC7A11 pathway." (PMID 41551515, 2025). "The downregulation of myeloid zinc finger 1 (MZF1) expression, which activates the Nrf2/GPX4 pathway and inhibits rankl-induced ferroptosis in osteoclasts during early cell differentiation, may be a key mechanism underlying ovarian removal (OVX) mice models of postmenopausal osteoporosis." (PMID 41551515, 2025).